CHEK2 (checkpoint kinase 2)
Diseases named in the same sentence as CHEK2 in open-access papers (continued):
Sharing a sentence is not in itself a finding about the gene and the disease.
Ewing sarcoma (7 papers, 2019 to 2025). A small round cell tumor that lacks morphologic, immunohistochemical, and electron microscopic evidence of neuroectodermal differentiation. "Moreover, germline mutations in the CHEK2 gene were overrepresented in some cohorts of patients diagnosed with Ewing sarcoma." (PMID 40040726, 2025). "Nominal enrichment of CHEK2 variants have been described among individuals with Ewing sarcoma." (PMID 36980535, 2023). "Germline pathogenic variants in DDR genes, including FANCC, CHEK2, and FANCA, have been reported as predisposing to the development of Ewing sarcoma." (PMID 40563612, 2025).
invasive breast carcinoma (7 papers, 2019 to 2025). A carcinoma that infiltrates the breast parenchyma. "Also, CHEK2 c.470T > C missense variant had similar prevalence (7.1%) in DCIS cases and invasive breast cancer cases (7.7%)." (PMID 40770660, 2025).
metastatic disease (7 papers, 2008 to 2026). "The inclusion of germline genetic testing for variants in genes such as BRCA1/2, ATM and CHEK2 are likely to be incorporated into mainstream testing for men presenting with locally advanced or metastatic disease." (PMID 33486571, 2022). "Furthermore, poorer survival related to the CHEK2 1100delC gene-expression signature highlights pathways that are likely to have a role in the development of metastatic disease in carriers of the CHEK2 1100delC mutation." (PMID 21542898, 2011). "Strikingly, ATM is the only cell cycle checkpoint kinase gene enriched for mutation in the primary setting, as both CHEK2 (P = 0.001) and ATR mutations (P = 0.0002) are enriched in metastatic disease." (PMID 37390209, 2023). "Two metastatic tumors (Cases 22 and 23) harbored heterozygous SMARCB1 deletions accompanied by broad 22q losses affecting CHEK2, NF2, and EP300." (PMID 41317331, 2026).
non-small cell lung carcinoma (7 papers, 2020 to 2025). A group of at least three distinct histological types of lung cancer, including non-small cell squamous cell carcinoma, adenocarcinoma, and large cell carcinoma. "For example, DNA methylation-mediated gene silencing of checkpoint kinase 2 (CHK2) was found to be associated with cisplatin resistance in non-small-cell lung carcinoma (NSCLC)." (PMID 34294135, 2021).
squamous cell carcinoma (7 papers, 2002 to 2025). A carcinoma arising from squamous epithelial cells. "Mutations of all; PALB2, BRCA1, BRCA2 and CHEK2 were most frequent in cutaneous squamous cell carcinomas covering ~60% of mutations in each of the genes." (PMID 34084283, 2021). "Both penile tumors (squamous cell carcinoma) exhibited mutations in BRCA1 and FAS, as well as ARID1A, CHEK2, BRCA2, and were Human Papillomavirus (HPV) positive." (PMID 41395625, 2025).
acute myeloid leukemia (6 papers, 2007 to 2025). Acute myeloid leukemia (AML) is a group of neoplasms arising from precursor cells committed to the myeloid cell-line differentiation. "In addition, deleterious CHEK2 variants are common germline alleles detected in MDS or acute myeloid leukemia (AML) patients undergoing inherited cancer risk testing." (PMID 40335619, 2025). "In public acute myeloid leukemia (AML) datasets, 1% (16/1348) of patients had P/LP CHEK2 variants." (PMID 40335619, 2025). "Additionally, mutations in CHEK2 and BRCA2 have been linked to CLL and MDS, RAD51 in acute myeloid leukemia (AML) and MDS, MLH1 in MDS, and BRCA1 in AML." (PMID 34840720, 2021).
brain cancer (6 papers, 2021 to 2025). A primary or metastatic malignant neoplasm affecting the brain. "Mutations in CHEK2 are responsible for an increased predisposition to breast, prostate, colon, stomach, and brain cancer." (PMID 37843608, 2023).
familial breast cancer (6 papers, 2007 to 2023).
mesothelioma (6 papers, 2012 to 2025). A usually malignant and aggressive neoplasm of the mesothelium which is often associated with exposure to asbestos.
thyroid tumor (6 papers, 2019 to 2025). A benign or malignant neoplasm affecting the thyroid gland. "A significant excess of malignancies of thyroid and other endocrine tumors (C73-C75) was observed in MyCode but not UK Biobank; this was almost entirely driven by thyroid tumors (C73) and, unlike most other associations, by CHEK2 PMV." (PMID 39371170, 2024).
acute lymphoblastic leukemia (5 papers, 2014 to 2026). Leukemia with an acute onset, characterized by the presence of lymphoblasts in the bone marrow and the peripheral blood. "However, to the best of our knowledge, B-acute lymphoblastic leukemia (B-ALL) has never been described as a presenting manifestation of germline CHEK2 mutation." (PMID 36937957, 2023).
ataxia telangiectasia (5 papers, 2010 to 2022). Ataxia-telangiectasia is the association of severe combined immunodeficiency (affecting mainly the humoral immune response) with progressive cerebellar ataxia. "Seven of these patients were found to carry two pathogenic variants including one biallelic ATM carrier with a clinical diagnosis of ataxia-telangiectasia, two ATM/BRCA2 carriers, one BRIP1/BRCA2 carrier, one BRCA1/CHEK2 carrier, one BARD1/PALB2 carrier, and one CHEK2/PALB2 carrier." (PMID 28008555, 2017).
chronic lymphocytic leukemia (5 papers, 2010 to 2021). "One of those CHEK2 variants is p.(Ile157Thr), which has been described to confer increased cancer risk for solid tumors and chronic lymphocytic leukemia." (PMID 33840814, 2021). "A strong association was also reported for the CHEK2 I157T mutation and an increased risk of chronic lymphocytic leukemia (OR = 14.83; P = 0.0008)." (PMID 26506619, 2015).
male breast carcinoma (5 papers, 2008 to 2025). A malignant neoplasm involving the male breast. "In a retrospective analysis of 715 cases of male breast cancer, BRCA2 and CHEK2 were the most frequently involved genes in hereditary male breast cancer." (PMID 39858629, 2025). "P/LP variants in BRCA1, BRCA2, PALB2, CHEK2, and ATM have been associated with male breast cancer." (PMID 39858629, 2025). "Notably, we found that CHEK2 and PALB2 were also associated with male breast cancer in GeneCards." (PMID 33959510, 2021).
ovarian tumor (5 papers, 2010 to 2022). "The CHEK2 c.1100delC mutation was found in a single case of a primary ovarian tumor with the FOXL2p.C134W somatic mutation, morphologically consistent with AGCT and positive by IHC for inhibin, FOXL2, calretinin, and SF1." (PMID 35267514, 2022). "All these data indicate that CHEK2 variants may predispose to a range of ovarian tumor types of low malignant potential." (PMID 32570972, 2020).
colon adenocarcinoma (4 papers, 2018 to 2025). "TSO/TSOE was also used to diagnose a 72-year-old woman who had had ascending colon adenocarcinoma at the age of 64 and with a family history of muscle disease; a known familial CHEK2 variant NM_007194.3(CHEK2):c.319+2T>A p.?" (PMID 36425062, 2022).
hereditary colorectal cancer (4 papers, 2022 to 2023). "Among the genes where a potentially pathogenic variant was identified, one of them was already associated with hereditary colorectal cancer, the CHEK2 gene." (PMID 35181726, 2022). "CHEK2 mutation is widely reported in sporadic colorectal cancer and hereditary colorectal cancer." (PMID 35530355, 2022).
multiple myeloma (4 papers, 2012 to 2024). "The action of SRT1720 on myeloma cells also increases the concentration of ATM kinase (ataxia-telangiectasia mutated kinase) and increases its ability to interact with the effector kinase involved in DNA repair—checkpoint kinase 2 (CHEK2)—which leads to cell death induced by this complex." (PMID 33435263, 2021).
myelodysplastic syndrome (4 papers, 2002 to 2025). A clonal hematopoietic disorder characterized by dysplasia and ineffective hematopoiesis in one or more of the hematopoietic cell lines. "Treatment discontinuations due to adverse events occurred in 51 patients (14.7%) in the niraparib and abiraterone group, including one case of myelodysplastic syndrome (in a patient with a CHEK2 germline mutation), and in 36 patients (10.3%) in the abiraterone group." (PMID 41057655, 2025). "Additionally, germline CHEK2 variants were also shown to be associated with cancer-predisposing disease, such as myelodysplastic syndrome." (PMID 36980535, 2023). "Small, single-center studies suggest that deleterious germline CHEK2 variants may contribute to the development of non-Hodgkin lymphoma (NHL), myeloproliferative neoplasms (MPNs), and myelodysplastic neoplasms (MDS)." (PMID 40335619, 2025).
myeloid leukemia (4 papers, 2021 to 2025). A clonal proliferation of myeloid cells and their precursors in the bone marrow, peripheral blood, and spleen. "A genome wide association study showed enrichment of CHEK2 loss-of-function variants with myeloid leukemia (P = 5.78e−7)." (PMID 40335619, 2025). "ATM and CHEK2 variants create a higher risk of generating chromosomal translocations and other mutations associated with myeloid leukemia development." (PMID 40766138, 2025). "We also observe that, on a population level, LoF CHEK2 variants associate with hematopoietic abnormalities and myeloid leukemias; although CHEK2 was below the conventional 5e−8 threshold for GWAS analysis, HMs are underrepresented in the UKBB, limiting sensitivity in this context." (PMID 40335619, 2025). "Within the UKBB, a GWAS for ICD-10 code C92 Myeloid leukaemia showed the strongest association with pLoF variants in the genes TET2 (P = 1.53e−25, β = 0.176629), EZH2 (P = 1.53e−8, β = 0.430923), and CHEK2 (P = 5.78e−7, β = 0.092176)." (PMID 40335619, 2025). "Other known myeloid leukemia predisposition genes, including DDX41 (P = 3.68e−4, β = 0.115770) and RUNX1 (P = 3.99e−4, β = 0.176099), were identified at a lower significance level than seen for CHEK2 pLoF variants." (PMID 40335619, 2025). "Interestingly, CHEK2 arises as one of the genes most strongly associated with myeloid leukemias by GWAS, suggesting a link between P/LP CHEK2 P/LP variants and myeloid leukemias, but not implying high penetrance." (PMID 40335619, 2025).
Obesity (4 papers, 2016 to 2025). Accumulation of substantial excess body fat. "With one-sided 95% CI, power was sufficient to exclude OR ≥2.0 with obesity for ATM and BRCA2; smoking and alcohol for CHEK2; no breastfeeding for ATM; no oophorectomy for BRCA2 and CHEK2; no tubal ligation for CHEK2; and neighborhood socioeconomic status for all genes." (PMID 40298171, 2025).
pancreatic neuroendocrine tumor (4 papers, 2019 to 2024). Pancreatic endocrine tumor, also known as pancreatic neuroendocrine tumor (PNET), describes a group of endocrine tumors originating in the pancreas that are usually indolent and benign, but may have the potential to be malignant. "Furthermore, MUTYH/CHEK2, BRCA2, CDKN2A, and TIMP3 have also been associated with pancreatic neuroendocrine tumors." (PMID 35163032, 2022).
pheochromocytoma (4 papers, 2019 to 2022). "Surface C is modified at Ser111 by CHEK2, whose missense substitution associates to retinal- and CNS-hemangioblastomas, pancreatic and renal cysts, RCC and pheochromocytoma." (PMID 30943211, 2019). "In pheochromocytoma and paraganglioma (PCPG), 0.64% of mutations were recurrent HRAS p.Q61R, and 0.36% were CHEK2 p.K152E." (PMID 30890735, 2019).
skin cancer (4 papers, 2014 to 2025). "This review consolidates existing evidence and suggests that mixed cancer syndromes, especially LFS, LS, and HBOC but also pathogenic ATM and CHEK2 variants may predispose individuals to skin cancers, warranting tailored screening and preventive measures." (PMID 41331641, 2025). "The evidence linking BRCA1/2, ATM, CHEK2, BRIP1, and FH pathogenic variants to increased skin cancer risk is limited." (PMID 41331641, 2025). "Further studies are necessary to explore the involvement of CHEK2 in the development of skin cancer." (PMID 37628581, 2023). "Studies on the link between CHEK2 and skin cancers have yielded mixed results." (PMID 41331641, 2025). "Rare biallelic CHEK2 mutations appear to increase the overall cancer risk, although a statistically significant increase in skin cancer risk has not been reported." (PMID 41331641, 2025). "Finally, we compare the frequency of mutations of the core HR genes BRCA1/2, CHEK2 and PALB2 in non-melanoma skin cancers." (PMID 34084283, 2021). "Similarly, whether the skin site was chronically exposed to UV radiation or not did not affect skin cancer detection in BRCA2, CHEK2, or CHEK2 1100delC pathogenic variant carriers." (PMID 41331641, 2025).
thyroid (4 papers, 2012 to 2025). "In conclusion, there is insufficient evidence to warrant systematic thyroid screening in CHEK2 carriers." (PMID 35101071, 2022).
-medullary thyroid cancer (3 papers, 2022 to 2025). "Publications from other geographic areas have confirmed only a modest risk increase in non-medullary thyroid carcinomas for monoallelic CHEK2 pathogenic variants." (PMID 40448797, 2025).
adrenocortical carcinoma (3 papers, 2022 to 2025).
B-cell lymphoma (3 papers, 2017 to 2021). "Targeted CHEK2 gene sequence analysis in another group of 340 patients from the Czech republic with different types of B-cell lymphoma revealed many germline variants of the CHEK2 gene including the well-known c.1100delC founder mutation." (PMID 28211887, 2017).
carcinoma in situ (3 papers, 2021 to 2023). "The segregation analysis, when available, highlighted two major results: CHEK2 variants c.793-1G>A and p.(Ile157Thr) were found in a ccRCC case and in a subject diagnosed with in situ melanoma, respectively." (PMID 37628581, 2023). "They found that loss of CHEK2 expression was associated with a worse progression-free survival, multifocal tumors, carcinoma in situ, and higher tumor grading (G3)." (PMID 34499690, 2021). "About a quarter of all ATM-related BCs and a third of CHEK2 BCs were in situ carcinomas and more than half of ATM and CHEK2-related BCs were diagnosed at stage I-II." (PMID 33919281, 2021). "About a quarter of all ATM-related BCs and a third of CHEK2 BCs were in situ carcinomas and more than half of ATM and CHEK2-related BCs were diagnosed at stage I-II (59.1% and 55%, respectively), whereas 13.6% of the ATM BCs and 15% of the CHEK2 BCs were stage III-IV." (PMID 33919281, 2021).
childhood cancer (3 papers, 2021 to 2025). "Germline CHEK2 variants are considered rare in pediatric cohorts, but childhood cancer patients have historically not been assessed for such variants, leading to a potential underestimation of the true prevalence." (PMID 36980535, 2023). "Next, by combination of the comprehensive clinical data of each patient with published data on VUSs, we identified six prioritized VUSs in CHEK2 and HOXB13 genes in seven patients for which we found strong evidence to confer an increased susceptibility to childhood cancer." (PMID 33840814, 2021). "Taken together, the seven prioritized VUSs in CHEK2 and HOXB13 genes might confer an increased risk for childhood cancer." (PMID 33840814, 2021).
cutaneous melanoma (3 papers, 2021 to 2025). A primary melanoma arising from atypical melanocytes in the skin. "Clinical studies evaluating the risk of cutaneous melanoma in CHEK2 mutation carriers have been reported in the literature." (PMID 40283643, 2025). "In our study, there was 1 individual with CHEK2-related DFSP who developed cutaneous melanoma, although the variant was p.(Ile157Thr) instead of p.(Thr367MetfsTer15)." (PMID 39669616, 2024).
ductal carcinoma in situ (3 papers, 2019 to 2025). "Case 7 was homozygous for CHEK2 c.1100delC variants and was diagnosed with invasive ductal tumor and abundant ductal carcinoma in situ at the age of 51 years, and had cancer recurrence five years after the initial diagnosis." (PMID 40009290, 2025).
endocrine tumors (3 papers, 2022 to 2025). "In this case report, two siblings with a germline CHEK2 mutation also had distinct endocrine tumors." (PMID 36440216, 2022). "Recently, CHEK2 mutations were described in the context of endocrine cancer: one patient with a germline CHEK2 mutation with ACC was reported, and a pathogenic variant of the gene was documented in a patient with multiple endocrine gland tumors." (PMID 36440216, 2022). "In this report, two siblings with a germline CHEK2 mutation and atypical endocrine tumor associations are described." (PMID 36440216, 2022). "In this case series, we describe two sisters with a germline CHEK2 mutation in addition to endocrine tumors that may have driver somatic mutations that could give rise to endocrine neoplasms." (PMID 36440216, 2022). "In this report, we describe two sisters sharing a CHEK2 c.1100delC mutation and presenting with endocrine tumors in a pattern not typical of classic multiple endocrine neoplasia." (PMID 36440216, 2022).
ependymoma (3 papers, 2015 to 2022). A WHO grade II, slow growing tumor of children and young adults, usually located intraventricularly. "ependymoma with cell-cycle-checkpoint kinase 2 (CHEK2) p.H371Y germline mutation." (PMID 34716641, 2021).
hereditary ovarian cancer (3 papers, 2015 to 2019).
Hodgkins lymphoma (3 papers, 2015 to 2025). A heterogeneous group of malignant lymphoid neoplasms of B-cell origin characterized histologically by the presence of Hodgkin and Reed-Sternberg (HRS) cells in the vast majority of cases. "We have recently reported an association of alterations localized within the CHEK2 FHA domain coding region with an increased risk of Hodgkin lymphoma (OR = 2.11; P = 0.04;." (PMID 26506619, 2015).
Li-fraumeni-like syndrome (3 papers, 2009 to 2020). "Germline CHEK2 P/LP variants have been associated with Li-Fraumeni like syndrome, BC, and other cancers, including prostatic, gastrointestinal, and, although still debated, OC." (PMID 32957588, 2020). "Mutations in the CHEK2 gene have also been reported in a few LFS and Li Fraumeni-like syndrome (LFL) families." (PMID 21059199, 2010).
non-Hodgkin lymphoma (3 papers, 2015 to 2025). Distinct from Hodgkin lymphoma both morphologically and biologically, non-Hodgkin lymphoma (NHL) is characterized by the absence of Reed-Sternberg cells, can occur at any age, and usually presents as a localized or generalized lymphadenopathy associated with fever and weight loss. "Studies have reported pathogenic germline CHEK2 loss-of-function alterations in non-Hodgkin lymphomas, including Burkitt lymphomas." (PMID 36980535, 2023). "The CHEK2 gene has been recognized as a multi-cancer susceptibility gene; however, its role in non-Hodgkin lymphoma (NHL) remains unclear." (PMID 26506619, 2015).